MIR302F (microRNA 302f)
Synonyms: hsa-mir-302f; MIRN302F
Gene: MicroRNA gene on chromosome 18 (30,298,910 to 30,298,960, forward strand). Ensembl gene ENSG00000283218.
Diseases named in the same sentence as MIR302F in open-access papers:
MIR302F is named in the same sentence as 3 diseases in open-access papers, as found by Europe PMC text mining. Sharing a sentence is not in itself a finding about the gene and the disease. The quoted sentences say what the papers report.
gout (2 papers, 2019 to 2024). A condition characterized by painful swelling of the joints, which is caused by deposition of urate crystals. "In addition, three genes (CNTN5, MIR302F, and ZNF724) were detected as ‘gout vs. asymptomatic hyperuricemia’-specific genetic factors." (PMID 38397902, 2024).
hippocampal atrophy (1 paper, 2019). "We identified genome-wide significant associations of 3 SNPs (rs4420638, rs56131196, rs157582) in the TOMM40-APOC1 region with hippocampal atrophy rate and 3 additional suggestive association loci (in TOMM40 gene and near MIR302F gene)." (PMID 31760383, 2019).
MIR302F also shares sentences with these, for which no sentence is quoted: hyperuricemia (1 paper).